MTOR (mechanistic target of rapamycin kinase)
Diseases named in the same sentence as MTOR in open-access papers (continued):
Sharing a sentence is not in itself a finding about the gene and the disease.
cancer (continued). "Several selective mTOR inhibitors are in development stage and more studies are warranted to further evaluate the efficacy of these agents in the treatment of cancers affected by hyperactive PI3K/mTOR pathway." (PMID 22408430, 2012). "The deregulation of many signaling pathways such as EGF/RAS/RAF/MEK/ERK and PI3K/AKT/mTOR is considered to play a critical role in oncogenesis and cancer progression." (PMID 24281308, 2012). "In cancer cells, the expression of constitutive active AKT, KRAS or the activation of the mTOR pathway has been associated with an increased Warburg effect and higher sensitivity to glucose deprivation." (PMID 22662165, 2012). "For these reasons, dual targeting of both Akt and mTOR, or directly inhibiting eIF4E activity, have been proposed as treatments for cancer." (PMID 22392765, 2012). "In summary, our data demonstrates that the class I PI3K/Akt/mTOR pathway is a major signaling axis in the survival of cancer cells." (PMID 22647622, 2012). "Ridaforolimus has been shown to inhibit mTOR and has demonstrated anti-proliferative activity against several cancer types in vitro and in vivo." (PMID 24300398, 2012). "The mammalian target of rapamycin (mTOR) has been emerged as an important cancer therapeutic target." (PMID 22559167, 2012). "Genetic alterations of mTOR pathway-related genes, including mutations of PI3K, AKT, and PTEN, facilitate tumorigenesis and are common in human cancers." (PMID 23209702, 2012). "NCT01347866 is a clinical trial for patients with advanced cancers combining the PI3K/mTOR inhibitors (PF-04691502 & PF-05212384) with the MEK inhibitor (PD-0325901) or irinotecan." (PMID 23085539, 2012). "The efficacy of these compounds should apply to tumor cells with a wide spectrum of oncogenic lesions because the Ras/EGFR/PI3K/mTOR pathway is activated in many types of cancer." (PMID 22452803, 2012). "Overall, the signaling network defined by Akt and the two mTOR complexes is a central driver of cell growth, metabolism, and proliferation, and the activity of this network is elevated in nearly all human cancers." (PMID 22888331, 2012). "To establish if autophagy suppression improves anti-cancer activity of mTOR inhibitors, we determined the functional role of autophagy activation by rapalogs and that autophagy inhibition enhanced the anti-tumor activity." (PMID 22848625, 2012). "Other studies have shown that APN-mediated AMPK activation signaling resulted in the inhibition of the mTOR pathway in CRC cell lines to suppress cancer cell growth." (PMID 23691481, 2012). "mTOR signaling is one of the major regulators of translation in cancer cells by altering 4EBP-1 and eIF4E activity." (PMID 23259068, 2012). "The activation of PI3K leads to further activation of mTOR which suppresses the expression of pro-apoptotic Bim and favors survival and proliferation of cancer cells." (PMID 22509328, 2012). "Antroquinonol induces anti-cancer activity in human pancreatic cancers through an inhibitory effect on PI3-kinase/Akt/mTOR pathways that in turn down-regulates cell cycle regulators." (PMID 22582152, 2012). "Protein Kinase B (PKB), also known as Akt, participates in the PI3K/Akt/mTOR pathway, a master regulator of aerobic glycolysis and cellular biosynthesis, two activities shown by both normal and cancer proliferating cells." (PMID 23181020, 2012). "The importance of mTOR and its inhibition in various conditions, including cancer, diabetes, aging and others has been further elucidated." (PMID 23455493, 2012). "PIK3CA and, recently, MTOR have been successfully targeted with selective agents to treat human cancers." (PMID 22912864, 2012). "It should come as no surprise, due to the significance of the regulatory activities of the PI3K/Akt pathway and its interaction with mTOR, that dysfunction of these signaling activities would alter cellular functions, as observed in most cancers." (PMID 23369283, 2012).
cancer (continued). "In this review, we have discussed the various types of mutations which occur in the Ras/Raf/MEK/ERK and Ras/PI3K/Akt/mTOR pathways and how they can lead to cancer as well as other diseases." (PMID 23006971, 2012). "An emerging concept in cancer therapy is the targeting of multiple points in the PI3K/PTEN/Akt/mTOR and other pathways." (PMID 23455493, 2012). "Translation inhibitors have shown promise in battling Ph+ cancers and the mTOR inhibitor rapamycin works synergistically with imatinib to stop proliferation of CML cell lines in vitro." (PMID 22693568, 2012). "As a result mTOR signalling is currently the most targeted signalling pathway in drug development for the treatment of cancers." (PMID 22479207, 2012). "The phosphoinositide-3-kinase (PI3K)/mammalian target of rapamycin (mTOR) pathway is frequently dysregulated in many human cancers, and inhibition of the mTOR pathway as a new therapeutic target is an active area of research." (PMID 22343617, 2012). "This pathway is also an important target for cancer treatment, including mammalian target of rapamycin (mTOR) inhibitors, inhibitors of PI3K and inhibitors of Akt that have already demonstrated clinical efficacy for different tumors." (PMID 22590527, 2012). "Consistent with the effects of anti-mTOR therapy in other cancers, inhibition of mTOR by rapamycin displays a potent antitumor effect in HNSCC in vitro, in oral carcinogenesis model, and in a HNSCC-GEMM." (PMID 22666248, 2012). "Everolimus (RAD001) is an allosteric mTOR inhibitor that has shown marked efficacy in certain cancers but is unable to completely inhibit mTOR activity." (PMID 23155392, 2012). "Dual PI3K/mTOR inhibitors have displayed significant, concentration-dependent cell proliferation inhibition and induction of apoptosis in a broad panel of cancer cell lines, including those harboring PI3K p110α activating mutations." (PMID 22564882, 2012). "The mammalian target of rapamycin (mTOR) is a central intracellular kinase that coordinates mitogenic, angiogenic, antiapoptotic, and survival pathways in cancers through crosstalk with VEGF, HIF-1, and the EGFR/ErbB family of RTKs." (PMID 22481932, 2012). "In the context of colorectal cancer, the treatment of cell lines with APN resulted in AMPK activation and suppression of mTOR pathway, thus inhibiting cancer cell growth." (PMID 23691481, 2012). "Because aberrant PI3K/AKT/mTOR signaling is a characteristic of almost all human cancers, a plethora of small molecule inhibitors exist that target various nodes of this pathway." (PMID 23316192, 2012). "Other cancer models have also identified mTOR signaling as a potential target for anticancer therapy." (PMID 23443110, 2012). "Soy isoflavones, at high levels, can induce apoptosis and growth arrest of cells through direct inhibition of mTOR in certain cancer cell lines." (PMID 23056418, 2012). "Combination of honokiol with the mTOR inhibitor rapamycin presents synergistic effects on induction of apoptosis of cancer cells." (PMID 23213333, 2012). "Cancer cells with activation of PI3K/mTOR signaling are more resistant to paclitaxel, and the co-administration of PI3K/mTOR inhibitors with paclitaxel improves therapeutic effects." (PMID 23077520, 2012). "Since the antitumor efficacy of rapalogues in patients is modest, activation of AKT as a central regulator of cell growth is a potentially unfavorable event resulting from cancer treatment with mTOR inhibitors." (PMID 23167739, 2012). "This pathway is frequently activated in malignancies, and inhibition of the mTor complex proteins Raptor and Rictor retards cancer cell invasiveness and suppresses the EMT required for metastasis." (PMID 23055980, 2012). "Various MEK inhibitors and PI3K/AKT/mTOR inhibitors are currently in clinical development, either as monotherapy or in combination therapy, for the treatment of various cancers." (PMID 22880048, 2012).
cancer (continued). "Inhibition of mTOR using rapamycin or its derivatives upregulates Ser473 phosphorylation of Akt in cancer cell lines and human tumours." (PMID 23300651, 2012). "Since previous reports have shown that FASN can be regulated by the mTor signaling pathway and USP2a-induced protein stabilization in cancer cells, we asked if the effect on FASN expression mediated by β-catenin involves these two pathways." (PMID 22485149, 2012). "Two thirds of these novel targeted anticancer agents inhibit kinases, including EGFR, Src, and mammalian target of rapamycin (mTOR) activated in cancer cells as well as in microenvironment cells and now several V-ATPases inhibitors are under trial." (PMID 22949815, 2012). "The presence and prognostic significance of inappropriate mTOR activation have been reported for several cancers." (PMID 22333597, 2012). "Deregulation of these tumour suppressors in cancer results in activation of the mTOR/S6K pathway and subsequent elevation of HIF-1α and VEGF, which promote tumour angiogenesis." (PMID 22570651, 2012). "More PIK3CA/AKT1 mutations and PIK3CA copy gain are identified in ATC as compared to well differentiated cancer, suggesting that PI3K/mTOR pathway activity is involved in the process of cancer de-differentiation." (PMID 23077520, 2012). "mTOR downstream effectors S6K1, 4EBP1 and eIF4E are implicated in cellular transformation, and their overexpression has been linked to poor cancer prognosis." (PMID 22408430, 2012). "Chemotherapeutic agent cisplatin can up-regulate mTOR survival pathway which confers drug resistance to cancer cells." (PMID 23056575, 2012). "There are no known predictive biomarkers for the efficacy or resistance in cancer of mTOR inhibitors." (PMID 22408430, 2012). "Other studies have shown that cancers with PIK3CA mutations were sensitive to single-agent PI3K inhibitors and dual PI3K-mammalian target of rapamycin (mTOR) inhibitors." (PMID 23056620, 2012). "Reports indicate that pharmacological activation of AMPK in cancer cells by either metformin or AICAR results in halting cell proliferation by negatively regulating mammalian target of rapamycin (mTOR) control of protein synthesis." (PMID 22548055, 2012). "The signaling of mTOR has been emerged especially as a critical effecter of PI3K signal transduction pathway in various human cancers." (PMID 23226337, 2012). "It has been shown that prolonged treatment of cancer cells or patients with mTOR inhibitors causes elevated PI3K activity that leads to phosphorylation of Akt and eIF4E, and promotes cancer cell survival." (PMID 22392765, 2012). "We genotyped 8 potentially functional polymorphisms in AKT1, AKT2, PTEN and MTOR genes using the TaqMan method in a case-control study of 710 RCC patients and 760 cancer-free subjects." (PMID 23209702, 2012). "The authors demonstrated, that transfection with miR-99a resulted in mTOR pathway inhibition and cell cycle arrest in that cancer." (PMID 22920721, 2012). "Adhesion plays also an important role in cancer metastasis and mammalian eIF4E and eIF4E-BPs have been shown to be involved via the mTOR pathway." (PMID 23226381, 2012). "MiR-328 has been shown to negatively regulate the expression of ABCG2 in human cancer cells, while miR-199a-3p has been shown to induce cell cycle arrest, reduce invasion, and increase doxorubicin sensitivity by negatively regulating mTOR and c-Met." (PMID 23176396, 2012). "mTOR has been implicated in the resistance of various cancers to EGFR inhibitors and mTOR pathway activation is a poor prognosticator of EOC." (PMID 22481932, 2012). "Accordingly, small-molecule inhibitors of PI3K/mTOR were shown to chemosensitize various cancers to a large variety of anticancer drugs, e.g., topoisomerase-1 or -2 inhibitors, platinum compounds, or microtubule interfering agents." (PMID 23061040, 2012).
cancer (continued). "Everolimus is a novel macrolide derivative of rapamycin that inhibits the ability of mTOR to phosphorylate S6K1 and 4EBP1, thereby causing G0/G1 arrest and inhibiting cell-cycle progression in cancer cells." (PMID 22343617, 2012). "Taken together, these data underscore the importance of mTOR signalling in cancer and reinforce the importance of considering mTOR targeting in cancer therapy." (PMID 22408430, 2012). "Peculiarly, mTOR, a negative regulator of autophagy, is over-active in most types of cancer, giving rise to several clinical trials involving inhibitors of mTOR in combination with anticancer agents to achieve better clinical outcomes." (PMID 24710490, 2012). "Overall, the in vitro activity of these ATP-competitive PI3K/mTOR modulators translated well in in vivo models of human cancer xenografted in mice." (PMID 22564882, 2012). "The mTOR pathway is explicitly correlated with the survival and the proliferation of cancer stem-like cells in human breast cancer by specific pathway inhibitors, gene knockdown and tumorigenicity assays in vivo." (PMID 23443123, 2012). "A negative feedback loop resulting in the activation of AKT following mTOR inhibition has been observed in a variety of cancer cell lines and human tumor samples of colon and breast cancer." (PMID 23167739, 2012). "Our results reveal that loss of miR-204 results in BDNF overexpression and subsequent activation of the small GTPase Rac1 and actin reorganization through the AKT/mTOR signaling pathway leading to cancer cell migration and invasion." (PMID 23285024, 2012). "The PI3K (phosphoinositide 3-kinase)/PTEN (phosphatase and tensin homologue deleted on chromosome ten)/Akt/mTOR (mammalian target of rapamycin) pathway is often involved in tumorigenesis and in sensitivity and resistance to cancer therapy." (PMID 22392765, 2012). "Our results show that loss of miR-204 promotes BDNF (or EGF)-induced cancer cell migration and invasion by activating AKT/mTOR pathway leading to Rac1 translocation and actin reorganization." (PMID 23285024, 2012). "The PI3K/Akt/mTOR signaling cascade belongs to the critical survival programs that are typically overactivated in human cancers and can promote cell survival by inhibiting the mitochondrial pathway of apoptosis." (PMID 23061040, 2012). "Growth factor signaling mediated by mammalian target of rapamycin (mTOR) drives metabolism of cancer cells by regulating expression of key enzymes in metabolic pathways." (PMID 22574221, 2012). "The mTOR signalling pathway is involved in controlling cell proliferation, growth and survival, and its dysregulation has been shown to commonly occur in cancers." (PMID 23284704, 2012). "In order to investigate how resveratrol is down regulating PKM2 expression, we looked into the mTOR signaling pathway, which is frequently dysregulated in cancers." (PMID 22574221, 2012). "mTOR signalling has been shown to be a critical pathway involved in tumour growth being the main target in the development of anti-cancer therapies." (PMID 22479207, 2012). "The PI3K/Akt/mTOR/p70S6K signaling pathways play a pivotal role in the physiological functions of human malignant tumors." (PMID 22460505, 2012). "Calorie restriction (CR) deactivates the nutrient-sensing mTOR pathway and delays both aging and cancer (and other age-related diseases)." (PMID 23565531, 2012). "Given that the PI3K/mTOR pathway is activated in both aging and cancer, aging and cancer share such characteristics as an increased metabolism, anabolic phenotype and other metabolic features." (PMID 23425920, 2012). "Clinical utility of mTOR inhibitors depends on appropriate selection of patients and type of cancer." (PMID 22214493, 2012). "Up to date, growing evidences have validated that the PTEN/AKT/mTOR axis are universally activated in numerous cancers including PCa, and inhibitors of these core genes are displaying great promise as the latent anticancer agents." (PMID 22815832, 2012).
cancer (continued). "It is considered to be a key negative regulator of the Akt/mTOR signaling, which is well known as a prosurvival pathway, suggesting perspective molecular target for anti-cancer research." (PMID 22363816, 2012). "Ridaforolimus (AP23573, MK-8669), a non-prodrug analog of rapamycin, is a potent and selective inhibitor of mTOR currently under clinical investigation as a targeted cancer." (PMID 22614157, 2012). "Because protein translation is central to both cancer growth and viral persistence, mTOR is a very important signaling protein." (PMID 23316192, 2012). "The idea of targeting mTOR as anticancer strategy emerged less than a decade ago and became rapidly a focus for cancer therapeutic developments." (PMID 22761648, 2012). "Recent development has made cancer treatment move on from conventional cytotoxic drugs to agents that target specific proteins like mTOR called mTOR inhibitors." (PMID 22214493, 2012). "Activation of the mTOR signalling is involved in some of the cancer hallmarks described by Hanahan and Weinberg." (PMID 22408430, 2012). "ATP-competitive mTOR inhibitors such as NVP-BEZ235 can block rapamycin-insensitive mTOR readouts and have entered clinical development as anti-cancer agents." (PMID 23155392, 2012). "VEGF-induced mTOR activation has been demonstrated to be necessary for angiogenesis in tumor models, while inhibition of VEGF and mTOR works synergistically to kill cancer cells and prevent tumor angiogenesis." (PMID 23029141, 2012). "What is common in cancer and senescence is the activation of growth-promoting signaling pathways such as mTOR." (PMID 23565531, 2012). "Given the importance of the mTOR pathway in cancer cell growth, significant efforts have attempted to identify targeted inhibitors." (PMID 22039466, 2011). "The combined application of mTOR inhibitor and docetaxel led to a greater degree of cancer cell killing than that by either compound used alone." (PMID 21392382, 2011). "I suggest that cell cycle arrest typically leads to senescence in cancer because cancer is a pro-senescent state (over-activation of mTOR-centric network) and cell cycle arrest simply allows its manifestation." (PMID 21297220, 2011). "Particularly, the role of mTOR in innate and adaptive immune cells needs to be further explored in the context of cancer." (PMID 24212820, 2011). "Future studies will need to develop optimal dosing strategies and identify cancer vaccines that are best suited for use with mTOR inhibitors." (PMID 21285988, 2011). "In this study, we examined the roles of mTOR in the maintenance and differentiation of cancer stem-like cells (CSCs), the conversion of conventional cancer cells to CSCs and continuous tumor growth in vivo." (PMID 22145042, 2011). "Mammalian target of rapamycin (mTOR) signaling is a master regulator of cellular proliferation and is an attractive therapeutic target for a variety of cancers." (PMID 21695255, 2011). "Over the last decade, extensive studies have been made to understand the role played by the mammalian target of rapamycin (mTOR) in cancer." (PMID 24212820, 2011). "Some promising recent observations indicate that certain CICs are sensitive to mTOR inhibitors, documenting their potential use in the elimination of the cells responsible for cancer re-emergence." (PMID 21411864, 2011). "Inhibitors of the kinase mTOR, such as rapamycin and everolimus, have been used as cancer therapeutics with limited success since some tumours are resistant." (PMID 21320304, 2011). "Increasing evidence indicates that the signaling pathways that activate mTOR are frequently improperly regulated in most human cancers." (PMID 22145042, 2011). "The mTOR pathway plays a crucial role in tumorigenesis and rapamycin and the other inhibitors of mTOR have been investigated as anti-cancer medications in recent years." (PMID 21283589, 2011).